EGFR (epidermal growth factor receptor)
Diseases named in the same sentence as EGFR in open-access papers (continued):
Sharing a sentence is not in itself a finding about the gene and the disease.
lung cancer (continued). "A broad range of cancer-associated proteins, including HER2, c-MET, MUC1, EGFR, and PD-L1, are also expressed in lung cancer." (PMID 41375062, 2025). "The epidermal growth factor receptor (EGFR) signaling pathway plays a crucial role in lung cancer development, with EGFR mutations and overexpression being key features of NSCLC." (PMID 40061935, 2025). "Targeted therapies have revolutionized cancer treatment, with successes such as HER2 inhibition in HER2-amplified breast cancer and EGFR-targeted therapies in EGFR-mutated lung cancer." (PMID 40588529, 2025). "ADCs using the T moiety–exatecan combination, such as those for EGFR‐del19/T790M/C797S triple mutation lung cancer, demonstrate prolonged antitumor effects in PDX models that accurately simulate challenging clinical scenarios." (PMID 39830019, 2025). "Histologic transformation to high-grade neuroendocrine carcinoma occurs in resistance to EGFR targeted treatment in approximately 3% to 4% of patients with EGFR-mutant lung cancer and is associated with poor outcomes." (PMID 41256964, 2025). "Emerging strategies for the treatment of advanced non‐small cell lung cancer (NSCLC) featuring epidermal growth factor receptor (EGFR) mutations are helping improve patient outcomes." (PMID 40515576, 2025). "Epidermal growth factor receptor (EGFR) mutations are a main actionable driver in non–small cell lung cancer (NSCLC)." (PMID 40768678, 2025). "The HCC827 cell line, with the EGFR Ex19Del mutation that accounts for ~ 60% of EGFR mutations in lung cancer, is highly responsive to first-generation EGFR TKIs, such as erlotinib." (PMID 40452841, 2025). "Non-small cell lung cancer (NSCLC), accounting for 85% of lung cancer cases, is frequently driven by oncogenic mutations in the epidermal growth factor receptor (EGFR) kinase domain." (PMID 40414926, 2025). "They investigated the impact of EGFR expression knockdown on the susceptibility of A549 lung cancer cells to EGCG." (PMID 40161336, 2025). "Compared to the 39% of patients’ samples with driver mutations and alterations who underwent sequencing of lung carcinomas at our institution, 76% of patients with CNS metastases harbored driver mutations and alterations, predominantly EGFR, KRAS, and ALK." (PMID 40423053, 2025). "On the contrary, lung carcinoma, while also subject to personalized approaches with drugs targeting EGFR mutations or ALK rearrangements and immunotherapy, generally shows lower overall response rates to chemotherapy compared to breast cancer." (PMID 40558249, 2025). "Non‐small cell lung cancer (NSCLC) represents the majority of lung cancer cases, with epidermal growth factor receptor (EGFR) mutations playing a crucial role in disease prognosis and treatment." (PMID 40855618, 2025). "The study was subsequently closed due to the changing landscape of treatment for advanced EGFR-mutated lung cancer." (PMID 39318388, 2024). "As an example, we examined EGFR, an oncogenic tyrosine kinase that is commonly mutated in diverse cancer types and cancer cell lines, including lung cancer, colorectal cancer, and glioblastoma." (PMID 39776849, 2024). "Germline EGFR T790M mutations are the most commonly reported PGVs in lung cancer, specifically in NSCLC." (PMID 38539485, 2024). "In lung cancer, meningeal carcinomatosis is frequently associated with adenocarcinoma histotype, oncogenic driver mutations like epidermal growth factor receptor (EGFR) mutation, and anaplastic lymphoma kinase (ALK) translocation." (PMID 38921299, 2024). "The Japan Lung Cancer Society conducted a nationwide survey of cancer center hospitals (345 facilities) with a focus on the detection rate of EGFR gene mutations." (PMID 39519246, 2024). "Yet another mechanism to upregulate PD-L1, frequently seen in types of lung cancer (but not limited to this), builds on a mutation in the EGFR pathway." (PMID 38339258, 2024).
lung cancer (continued). "We perform saturation mutagenesis of EGFR and assess function of ~22,500 variants in a human EGFR-dependent lung cancer cell line." (PMID 38548752, 2024). "This study aimed to assess the differences in EGFR mutation detection between two companion diagnostic (CDx) tests—the Oncomine Dx Target Test (ODxTT) and the AmoyDx Pan Lung Cancer PCR Panel—and their impact on treatment applicability." (PMID 38238401, 2024). "Lung cancer EVs containing a mutated form of EGFR (EGFR E746-A750) stimulated immunosuppressive activity in dendritic cells (DCs)." (PMID 39697631, 2024). "Increased EGFR/c-Met signaling in lung cancer patients is associated with shorter survival, suggesting that the interplay between EGFR and c-Met signaling plays a crucial role in lung tumor progression and development of resistance to TKI treatments." (PMID 38877005, 2024). "Different mutant variants of EGFR were identified in the blood of lung cancer patients using this model." (PMID 39611045, 2024). "Third, we hadn’t determined the relevance among prognosis and EGFR mutation subtypes in early-stage lung cancers." (PMID 38528507, 2024). "Compared to the suppressive tumor immune microenvironment in advanced-stage disease, there are still immune responses and immune cell infiltration in early-stage EGFR-mutated lung cancer." (PMID 38637495, 2024). "Our study revealed that CNNs trained with FDG-PET/CT data performed well in predicting EGFR mutation status in lung cancer." (PMID 39735601, 2024). "In this study, we evaluated the efficacy of a 4G EGFR-TKI in the treatment of lung cancer with EGFR mutation as well as explored resistance mechanisms to a 4G TKI." (PMID 39061985, 2024). "The ESMO Congress 2023 notably highlights the efficacy of combining targeted drugs and immunotherapy, especially for lung cancer patients with EGFR mutations and rare tumor alterations." (PMID 38474400, 2024). "Previous studies have successfully utilized blood ctDNA to determine the mutational status of the epidermal growth factor receptor (EGFR) and establish connections between EGFR mutations in ctDNA and the progression status of lung cancer." (PMID 38561776, 2024). "Serum SOD2 has been shown to be positively associated with all-cause mortality in lung cancer patients and resistance to EGFR-tyrosine kinase inhibitors in NSCLC." (PMID 38082189, 2024). "For example, afatinib has shown clinical efficacy against lung cancers harboring exon 19 deletions, L858R substitutions, or some other EGFR activating mutations located in exons 18–21 of the EGFR gene." (PMID 38612902, 2024). "First, the survival rate in the lung cancer cohorts with EGFR mutations was found to be lower than that in the cohort with wild-type EGFR." (PMID 38499532, 2024). "As previously noted, CAFs that express PDPN in lung cancer patients have been found to be resistant to EGFR/TKI drugs, such as Gefitinib, and are associated with poor outcomes." (PMID 39403603, 2024). "EGFR is often mutated or overexpressed in lung cancer, leading to uncontrolled cell growth and division." (PMID 38905286, 2024). "The next-generation sequencing (NGS; Ion AmpliSeq Colon and Lung Cancer Research Panel v2) of the tumour DNA revealed a classical epidermal growth factor receptor (EGFR) mutation in exon 21 (p.L858R; c.2573T > G)." (PMID 38891886, 2024). "With the rapid development of targeted and immunotherapy, these treatments have emerged as new approaches for lung cancer, particularly for patients with specific genetic mutations, such as EGFR or ALK mutations." (PMID 39640262, 2024). "For instance, a comprehensive study revealed the presence of EGFR p.T790M germline mutation (0.15%) in plasma Cell-free DNA (cfDNA) from lung cancer." (PMID 39389944, 2024).
lung cancer (continued). "The gefitinib-resistant lung cancer cell line (PC9GR) is established from its parental sensitive line (PC9) with a traditional EGFR mutation after long time exposure to gefitinib, which shows a quite different transcription, signaling, and metabolic profiles." (PMID 38398217, 2024). "Its multiplexing capability is showcased with a quadruplex dPCR assay that detects key EGFR mutations, including 19Del, L858R, and T790M in lung cancer." (PMID 38516754, 2024). "Dynamic metabolic characteristics have been the subject of numerous prior studies in tumor differential diagnosis; nevertheless, there are relatively few studies predicting the pathological type of lung cancer or EGFR mutations." (PMID 38730287, 2024). "EGFR mutation status analysis becomes one of the important factors in therapeutic strategies for lung cancer and is recommended for tumor resection, even the earliest stage lung cancer." (PMID 38528507, 2024). "Second, YY1 was evaluated in four lung cancer patients who harbored somatic EGFR mutations and received off-label neoadjuvant targeted therapies." (PMID 39604408, 2024). "Further study is necessary to discover improved treatment strategies for EGFR mutant lung cancer patients with DUSP22 loss or downregulation." (PMID 38877005, 2024). "GPX4 is upregulated in many patients with lung cancers and causes resistance to epidermal growth factor receptor-tyrosine kinase inhibitors (EGFR-TKIs), radiotherapy, and immune checkpoint inhibitors." (PMID 39104501, 2024). "The single-nucleotide substitution L858R in exon 21 comprises around 40% of all EGFR mutations in lung cancer patients." (PMID 39021764, 2024). "This is the first in vivo transcriptional evidence that, similarly to KRAS-mutant AT2 cells, AT2 cells carrying EGFR mutations act as lung cancer cells of origin." (PMID 38546390, 2024). "The phase III IMPACT study (UMIN000044738) compared adjuvant gefitinib with cisplatin plus vinorelbine (cis/vin) in completely resected epidermal growth factor receptor (EGFR)‐mutated non‐small cell lung cancer (NSCLC)." (PMID 37864465, 2024). "Overall, acknowledging the prognostic implications of EGFR mutations in lung cancer with ILAs can greatly influence clinical decision-making." (PMID 38783331, 2024). "These organoids consist of lung cancer cells harboring specific EGFR mutations, human mesenchymal stem cells, and human umbilical vein endothelial cells." (PMID 39766891, 2024). "Our study provides a systematic and comprehensive description of EGFR variant functionality in models of lung cancer." (PMID 38548752, 2024). "The second genetic mechanism that we describe underlying multiple EGFR-mutant primary lung cancers extends the observation of rare familial lung cancer to cases without such pedigrees." (PMID 39406916, 2024). "Non-invasive saliva tests for lung cancer can identify cancer-related mutations like epidermal growth factor receptor (EGFR) gene mutations." (PMID 39211674, 2024). "Another potential explanation for the higher proportion of never-smokers in Chinese populations with SCLC is an early transformation of EGFR mutation-positive lung cancer." (PMID 38992123, 2024). "Advanced lung cancer patients with EGFR mutation (mut) and ALK rearrangement were enrolled to study, retrospectively." (PMID 38668879, 2024). "This suggests that individual characteristics of patients are associated with the incidence of EGFR-mutant lung cancer, which is consistent with the findings of Zhang and Shigematsu." (PMID 38555474, 2024). "NSCLC with classic EGFR mutations (19 deletions and L858R) is a prominent example and accounts for 80%–90% of lung cancer driver mutations." (PMID 38774882, 2024). "In more detail, this approach was applied to the H1650 and HCC827 human lung cancer cell lines that displayed different responsiveness to gefitinib, an EGFR tyrosine kinase inhibitor, due to an EGFR Exon 19 mutation." (PMID 38539567, 2024).
lung cancer (continued). "As osimertinib is the treatment of choice for lung cancer harboring EGFR mutations, we investigated the expression of β-galactosidase, characteristic of the senescent-like phenotype, in the residual cells after exposure to osimertinib." (PMID 39001552, 2024). "Lung cancer is one of the most common carcinomas reported globally, with mutated EGFR being the usual driver of gene mutation." (PMID 39144617, 2024). "These mutations make tumors highly responsive to EGFR tyrosine kinase inhibitors (TKIs), although their role in surgically resectable lung cancer is still debated." (PMID 39682234, 2024). "Advanced lung cancer patients with EGFR mutations typically show hypersensitivity to the tyrosine kinase inhibitors (TKIs) gefitinib and erlotinib." (PMID 39239557, 2024). "Epidermal growth factor receptor (EGFR) mutations are the most common mutations in non‐small cell lung cancer (NSCLC)." (PMID 38279684, 2024). "Here, the authors show that EGFR lung cancer mutations promote the assembly of kinase-active dimers within ligand-free EGFR oligomers." (PMID 38503739, 2024). "The co-expression of PD-L1 and CD8 in EGFR-mutated or ALK-rearranged lung cancer serves as a biomarker for poor prognosis, correlating with a shorter OS." (PMID 38397899, 2024). "For example, epidermal growth factor receptor (EGFR) mutations have been identified as predictive biomarkers for the response to targeted therapies in lung cancer." (PMID 38733011, 2024). "Recent advancements emphasize the importance of targeting common mutations, such as those in the epidermal growth factor receptor (EGFR), particularly the L858R variant within the tyrosine kinase domain implicated in lung cancer." (PMID 39469218, 2024). "Epidermal growth factor receptor (EGFR) tyrosine kinase inhibitors (TKIs) are used in the treatment of non–small cell lung cancer (NSCLC) with EGFR mutations." (PMID 39430640, 2024). "In China, approximately 20%–40% of the general population harbors mutations related to lung cancer, with the EGFR mutation present in 40%–50% of lung cancer patients." (PMID 38234199, 2024). "This review article explores diagnostic technologies for lung cancer with EGFR exon 20 insertion mutations and summarizes the latest clinical studies on therapeutic developments." (PMID 38892105, 2024). "As PARP4 copy number loss was associated with EGFR and KRAS mutations, we selected two additional classic lung cancer cell lines bearing EGFR or KRAS mutations that had moderate basal PARP4 expression." (PMID 39034402, 2024). "Another factor includes hormonal influence—an overexpression of estrogen receptors in adenocarcinomas, the role of aromatase in carcinogenesis of lung cancer and a relationship between estrogens and EGFR mutations." (PMID 38592288, 2024). "Future translational studies are needed to test TKIs of EGFR/c-Met and PD-L1 blockade to inhibit lung cancer progression resulting from loss of DUSP22 function." (PMID 38877005, 2024). "Epidermal growth factor receptor (EGFR) tyrosine kinase inhibitors (TKIs) have revolutionized the treatment of lung cancer patients with mutated EGFR." (PMID 38764025, 2024). "For this study, we wanted to evaluate and expand EGFR variant function under a more physiological context and therefore developed a lung cancer model system for this purpose." (PMID 38548752, 2024). "In lung cancer, CT-based radiomics have been used to predict EGFR mutation status, potentially guiding treatment decisions." (PMID 39518426, 2024). "For instance, it has shown high effectiveness in predicting IDH status in glioma and EGFR mutations in lung cancer." (PMID 39247207, 2024). "The EGFR P644S variant displayed a phenotype more closely associated with EGFR WT in each of the tested lung cancer models." (PMID 38548752, 2024). "For example, the lung cancer associated P1019L mutation in EGFR has already been shown to switch the binding specificity of the adjacent phosphorylation site pY101632." (PMID 38605029, 2024).
lung cancer (continued). "Consistent with previous reports, the TTNT of ICIs was superior in lung cancer with EGFR minor mutation than that with EGFR major mutation; however, the benefit in OS was inverse." (PMID 38347279, 2024). "We present the case of a 75-year-old female with simultaneous EGFR-mutated stage IV lung cancer and advanced BRCA2-mutated ovarian cancer, treated with a unique regimen." (PMID 38275832, 2024). "The discovery of EGFR activating mutations in select lung cancer patients has led to the introduction of EGFR-TKIs for the treatment of NSCLC, particularly in patients harboring these EGFR mutations." (PMID 38904022, 2024). "Dactinib irreversibly inhibits EGFR and is the first-line treatment for patients with EGFR mutation-positive advanced lung cancer, with activity against all 3 kinase-active ErbB family members (EGFR/HER-1, HER-2, and HER-4)." (PMID 38983928, 2024). "In contrast, most MRI imageomics studies of brain metastases aim to distinguish between different lung cancer subtypes or primary sites, with a limited number focused on predicting EGFR mutation status in lung cancer." (PMID 38773634, 2024). "This study investigated demographic and clinical factors associated with mutant EGFR-TK positivity in patients with primary advanced-stage (IV) lung cancer." (PMID 39429333, 2024). "Noteworthy, the individual characteristics of patients, including gender, age and smoking status, are also related to the incidence rate of EGFR mutation-driven lung cancer." (PMID 38555474, 2024). "The occurrence of EGFR mutations in individuals diagnosed with lung cancer generally results in a positive reaction to targeted treatment, which contributes to prolonged survival." (PMID 38250731, 2024). "In this study, we aimed to investigate the prevalence of HPV and its genotypes and the relation with EGFR mutations, p16 protein expression and clinicopathological findings in lung cancer." (PMID 39205175, 2024). "Biological evaluation of the retrieved hit compounds showed suppressing activity against EGFR auto phosphorylation and selective apoptosis-induced effects toward lung cancer cells harboring the EGFR L858R/T790M double mutation." (PMID 38625872, 2024). "TMB was significantly higher in lung cancer patients with EGFR-sensitive mutations and high PD-L1 expression." (PMID 38238740, 2024). "Several genetic variants, such as BRCA2 and CHEK2, as well as germline mutations in the EGFR, specifically the mutations in exon 20 and exon 21, have been strongly associated with an increased risk of lung cancer." (PMID 39389944, 2024). "A retrospective cohort study was conducted to identify factors associated with progression-free survival (PFS), overall survival (OS) and response rate in stage IV lung cancer patients with EGFR mutations." (PMID 39421175, 2024). "Currently, the second- and third-generation TKIs afatinib and osimertinib, which irreversibly bind to the kinase domain of the EGFR, have become the leading choice of treatment for lung cancer harboring EGFR mutations." (PMID 39001552, 2024). "The management of lung cancer (LC) requires the analysis of a diverse spectrum of molecular targets, including kinase activating mutations in EGFR, ERBB2 (HER2), BRAF and MET oncogenes, KRAS G12C substitutions, and ALK, ROS1, RET and NTRK1-3 gene fusions." (PMID 38966170, 2024). "This particular form of lung cancer is linked to multiple mutations, involving those that occur in the human epidermal growth factor receptor (EGFR)." (PMID 39091946, 2024). "The adenocarcinoma histology of this EGFR-mutated tumor fits well with previous reports preferentially describing mutations in this histologic lung cancer subtype." (PMID 38770472, 2024). "Epidermal growth factor receptor (EGFR) gene mutations are the most prevalent targeted driver mutations in lung cancer." (PMID 39252824, 2024). "Radiomic models have shown good to excellent performance in predicting EGFR mutations in lung cancer." (PMID 39252824, 2024).